SUSD2 (sushi domain containing 2)
Description:
May be a cytokine receptor for GPR15LG. May be a tumor suppressor; together with GPR15LG has a growth inhibitory effect on colon cancer cells which includes G1 cell cycle arrest. May play a role in breast tumorigenesis.
Synonyms: BK65A6.2; FLJ22778; W5C5
Tractability: Antibody: UniProt places it where antibodies can reach, with high confidence; its Gene Ontology location is reachable by antibodies, with high confidence; UniProt predicts a signal peptide or a membrane-spanning region; the Human Protein Atlas places it where antibodies can reach.
Gene: Protein-coding gene on chromosome 22 (24,181,481 to 24,189,111, forward strand). Ensembl gene ENSG00000099994.
Subcellular location: Cell membrane
Subcellular location (Human Protein Atlas): Plasma membrane
Gene Ontology:
Molecular function: protein binding
Biological process: negative regulation of cell cycle G1/S phase transition; negative regulation of cell division
Cellular component: extracellular exosome; plasma membrane
Genetic constraint (gnomAD): Loss-of-function variants: 88 observed, 92.32 expected, observed/expected ratio (o/e) 0.95, 90% interval 0.8 to 1.14. The upper end of that interval is the gene's LOEUF score, 1.14, which puts it in group 4 of 6, group 1 being the genes least tolerant of losing a copy. Missense variants: 1,060 observed, 1,114.7 expected, observed/expected ratio (o/e) 0.95, 90% interval 0.9 to 1. Synonymous variants: 483 observed, 481.65 expected, observed/expected ratio (o/e) 1, 90% interval 0.93 to 1.08.
Homologues: Orthologues: chimpanzee SUSD2 (99% identical), macaque SUSD2 (91% identical), dog SUSD2 (77% identical), guinea pig SUSD2 (77% identical), pig SUSD2 (76% identical), mouse Susd2 (76% identical), rat Susd2 (75% identical), rabbit SUSD2 (67% identical), tropical clawed frog susd2 (53% identical), zebrafish SUSD2 (41% identical), Drosophila melanogaster mesh (32% identical), Caenorhabditis elegans dec-7 (31% identical), and 2 more. Paralogues in human: MUC4 (22% identical), RTL9 (15% identical).
Diseases named in the same sentence as SUSD2 in open-access papers:
SUSD2 is named in the same sentence as 52 diseases in open-access papers, as found by Europe PMC text mining. Sharing a sentence is not in itself a finding about the gene and the disease. The quoted sentences say what the papers report.
breast carcinoma (19 papers, 2014 to 2025). "Next, we sought to investigate the association between SUSD2 expression and survival in various breast cancer subtypes." (PMID 39791720, 2024). "We found that SUSD2 levels were increased in an EGFR+ cell line overexpressing HER2 and that SUSD2 levels were associated with poor patient survival in HER2+ breast cancer." (PMID 39791720, 2024). "A recent study of SUSD2 in breast cancer patients has implicated SUSD2 in the recruitment of tumor associated macrophages by inducing increased cancer cell secretion of Monocyte Chemoattractant Protein-1 (MCP-1)." (PMID 32595828, 2020). "Finally, we analyzed the association between patient survival and SUSD2 expression in breast cancer." (PMID 39791720, 2024). "Although our study partially demonstrated the clinical implications of SUSD2 in EGFR+ HER2+ breast cancer by showing that SUSD2 conferred a poorer survival to EGFR+ HER2+ breast cancer patients and that it was associated with EGFR and HER2 signaling, further mechanistic validation is necessary." (PMID 39791720, 2024). "CTC-ITB-01 showed by far the highest SUSD2 levels in the ER-α positive analyzed breast cancer cell lines." (PMID 39890941, 2025). "On a breast cancer tissue microarray, 82% of the samples were positive for SUSD2, including 41 of 47 estrogen receptor positive samples." (PMID 39890941, 2025). "Breast tumor tissues with HER2 amplification show a higher staining intensity of SUSD2 than tissues of other breast cancer subtypes." (PMID 39791720, 2024). "Our previous results indicated that SUSD2 was upregulated in HER2-overexpressing cells and that such an upregulation was associated with the poor survival of HER2+ breast cancer patients." (PMID 39791720, 2024). "According to the literature, SUSD2 interacts with Galectin-1, facilitating tumor immune evasion, angiogenesis, and metastasis in breast cancer." (PMID 39247587, 2024). "These previous reports collectively demonstrate that SUSD2 serves two-sided functions, such as pro-tumoral or anti-tumoral ones, depending on cancer type, including hepatocellular carcinoma, breast cancer, renal cell carcinoma, lung cancer, and ovarian cancer." (PMID 39791720, 2024). "We also found that SUSD2 expression was positively correlated with HER2 expression in a publicly available human primary breast cancer dataset." (PMID 39791720, 2024). "Our findings suggest the clinical significance of SUSD2 as a biomarker for EGFR+ HER2+ breast cancer and highlight the use of STAT3-specific inhibitors for treating EGFR+ HER2+ breast cancer expressing SUSD2." (PMID 39791720, 2024). "Sushi domain-containing protein 2 (SUSD2), a transmembrane protein containing a sushi motif, has been reported to have tumor-promoting functions in various types of cancer, including breast cancer." (PMID 39791720, 2024). "It is through the induction of apoptosis of Jurkat T cells that SUSD2 enhances the invasion of breast cancer cells and contributes to a possible immune evasion mechanism." (PMID 38206646, 2024). "In this study, we explored the potential of targeting SUSD2 to overcome trastuzumab (TRZ) resistance in HER2+ breast cancer." (PMID 39791720, 2024). "Through kinase array experiments, we found that SUSD2 expression was modulated downstream of STAT3-dependent signaling in breast cancer cells overexpressing HER2." (PMID 39791720, 2024). "Since we found that SUSD2 expression was increased in HER2-overexpressing cells, we examined SUSD2 expression levels in breast cancer cells with various subtypes." (PMID 39791720, 2024). "Although the sample size is limited, these clinical sample results further corroborate our findings on STAT3-mediated SUSD2 upregulation in EGFR+ HER2+ breast cancer, underscoring the clinical significance of SUSD2 expression." (PMID 39791720, 2024).
breast carcinoma (continued). "IHC staining revealed elevated SUSD2 protein levels in tissues from a patient (Case 1) with EGFR+ HER2+ breast cancer compared to tissues from a patient (Case 2) with EGFR+ breast cancer." (PMID 39791720, 2024). "Since our previous results demonstrated the upregulation of SUSD2 in EGFR+ HER2+ breast cancer cells, we aimed to further explore this association in clinical samples." (PMID 39791720, 2024). "Using a patient survival database, we found that SUSD2 expression was inversely correlated with the survival of HER2+ breast cancer patients." (PMID 39791720, 2024). "Sushi domain containing 2 (SUSD2) plays a significant role in tumorigenesis, which has been identified as a regulator of colon and breast cancer." (PMID 37644393, 2023). "The Sushi Domain Containing 2 (SUSD2) is a cell membrane protein with adhesion domains that interacts with Galectin-1 to promote breast cancer immune evasion, angiogenesis, invasion and metastasis." (PMID 36038558, 2022). "SUSD2 chaperones Gal-1 to the cell surface of breast cancer cells, which has potential implications for immune evasion in breast cancer." (PMID 31387209, 2019). "And as a novel molecule related with cancer migration, there were various phenotype assays indicated that Sushi Domain Containing 2 (SUSD2) increases the migration of breast cancer cells." (PMID 29636641, 2018). "Their study described that the interaction of SUSD2 with Gal1 increased the invasion of breast cancer cells and contributed to a potential immune evasion mechanism through induction of apoptosis of Jurkat T cells." (PMID 26933386, 2016). "Next, we analyzed the SUSD2 expression in CTC of patients with breast cancer." (PMID 39890941, 2025). "In this study, we explored the function of SUSD2 in the context of HER2+ breast cancer." (PMID 39791720, 2024). "Additionally, in vivo studies using EGFR+ HER2+ breast cancer models will be crucial to explore both the cancer-intrinsic and -extrinsic functions of SUSD2." (PMID 39791720, 2024). "Additionally, SUSD2 mRNA levels were higher in EGFR+ HER2+ breast cancer than in EGFR+ breast cancer." (PMID 39791720, 2024). "In this study, we found that SUSD2 was a novel target in EGFR+ HER2+ breast cancer." (PMID 39791720, 2024). "Although previous studies have demonstrated an association between SUSD2 and breast cancer progression, the specific role of SUSD2 in HER2+ breast cancer remains unclear." (PMID 39791720, 2024). "Conversely, the role of SUSD2 in breast cancer may be tumorigenic in nature; overexpression of SUSD2 in MDA-MB-231 cells has been shown to increase invasion through matrigel and induce T cell apoptosis in co-culture experiments." (PMID 32595828, 2020). "The SUSD2 gene is involved in the invasiveness of breast cancer cells and tumor evasion." (PMID 32962629, 2020). "Our studies have been focused on the role of SUSD2 in breast cancer." (PMID 31387209, 2019). "Targeting SUSD2’s post-translational processing steps may provide novel mechanisms for combating the pro-tumor effects of SUSD2 and Gal-1 in breast cancer." (PMID 31387209, 2019). "Details of post-translational processing of SUSD2 may reveal critical steps that could be targeted therapeutically to inhibit the function of SUSD2 in breast cancer." (PMID 31387209, 2019). "Discovery of the identity of this protease could prove useful in targeting SUSD2 production as a therapeutic intervention in breast cancer by preventing Gal-1 surface presentation." (PMID 31387209, 2019). "Summary of SUSD2 staining of 175 breast cancer patient samples." (PMID 28475599, 2017). "Because SUSD2 recruits macrophages into the TME and promotes M2 polarization, inhibiting the function of SUSD2 may be an effective therapy for breast cancer patients." (PMID 28475599, 2017). "Additionally, increased levels of MCP-1 were observed in Susd2-expressing mammary tumors isolated from our isogeneic mouse model." (PMID 28475599, 2017).
breast carcinoma (continued). "Their results suggested SUSD2 as an oncogene in breast cancer." (PMID 26933386, 2016). "However, in brain and CNS cancer, breast cancer, liver cancer, SUSD2 expression was lower." (PMID 32194777, 2020). "Therefore, identification and inhibition of this protease may provide a new therapeutic tool for inhibiting SUSD2 and Gal-1′s combined tumorigenic function in breast cancer." (PMID 31387209, 2019). "SUSD2′s pathogenicity in breast cancer may be mediated through Galectin-1 (Gal-1)." (PMID 31387209, 2019). "Collectively, our results demonstrate that SUSD2 expression is mediated by STAT3 and imply the potential of using SUSD2 as a biomarker to stratify HER2+ breast cancer." (PMID 39791720, 2024). "However, we could not observe any significant association between SUSD2 expression and survival in breast cancer patients with other subtypes such as the basal subtype or the luminal A subtype." (PMID 39791720, 2024). "In this study, we identified the role of SUSD2 in the prognostic aspect and verified how SUSD2 is regulated in EGFR+ and/or HER2+ breast cancer." (PMID 39791720, 2024). "The transmembrane protein, Sushi Domain Containing 2 (SUSD2), has been previously shown to be required for Gal-1 surface presentation in breast cancer cells." (PMID 31387209, 2019). "Endogenous SUSD2 expression was observed in HER2+ breast cancer cells but not in estrogen receptor-positive or triple-negative breast cancer cells." (PMID 39791720, 2024). "Additionally, SUSD2 levels were upregulated in SKBR3 and JIMT1 cell lines, which are EGFR+ HER2+ breast cancer cell lines." (PMID 39791720, 2024). "Furthermore, in a publicly available breast cancer patient dataset (GSE1456), SUSD2 expression levels were found to be upregulated in HER2+ breast cancer subtypes, including the luminal B and HER2 subtypes." (PMID 39791720, 2024). "This reduction in IL-1B, a pro-inflammatory cytokine involved in cancer progression, suggests that SUSD2 might influence inflammatory responses and tumor microenvironment dynamics in HER2+ breast cancer." (PMID 39791720, 2024). "Our results showed that SUSD2 expression had a negative correlation with the relapse-free survival of patients with EGFR+ HER2+ breast cancer when compared to EGFR+ breast cancer patients." (PMID 39791720, 2024). "Furthermore, STAT3 inhibitors such as C188-9 and Stattic not only reduced SUSD2 levels, but also suppressed cell growth and cell cycle progression in EGFR+ HER2+ breast cancer cell lines." (PMID 39791720, 2024). "Through human kinase arrays, we found that STAT3 signaling was activated in EGFR+ HER2+ breast cancer and that the inhibition of STAT3 led to the downregulation of SUSD2 levels, indicating that STAT3 was responsible for upregulated SUSD2 levels in EGFR+ HER2+ breast cancer." (PMID 39791720, 2024). "Sushi Domain Containing 2 (SUSD2) has been identified as a regulator of colon and breast cancer." (PMID 26933386, 2016). "SUSD2 expression had negative effects on the prognosis of EGFR+ HER2+ breast cancer patients." (PMID 39791720, 2024). "Unlike the oncogenic function of SUSD2 in breast cancer, this result suggests that SUSD2 may function by attenuating tumorigenesis in HGSOCs." (PMID 27775699, 2016). "Because HGSOC does not require angiogenesis as a means of metastasis, whereas breast cancer almost exclusively relies on angiogenesis to metastasize, the role of SUSD2 as observed in breast cancer may not manifest any obvious advantage in dissemination in HGSOC." (PMID 27775699, 2016). "However, the regulatory mechanism of SUSD2 and its function in HER2-positive (HER2+) breast cancer have not been fully identified as yet." (PMID 39791720, 2024).
lung carcinoma (9 papers, 2010 to 2025). "Few studies have reported an association between SUSD2 and different malignancies such as lung cancer or breast and renal cell carcinoma, where it acts as a tumour suppressor gene, with low levels being associated with aggressiveness." (PMID 40004202, 2025). "Only one SUSD2 mRNA variant has been described to date; however, splice array data suggested lung cancer-associated changes close to the 5' and 3' ends of the mRNA." (PMID 20525254, 2010). "SUSD2 is type I membrane protein containing domains inherent to adhesion molecules, in which downregulation was associated with proliferative capacity renal cell and lung carcinomas and other cancers." (PMID 31426508, 2019). "The restoration of SUSD2 expression inhibited the proliferation and clonogenicity of lung cancer cells." (PMID 32194777, 2020). "The reduced SUSD2 expression level in lung cancer tissues was positively correlated with poor histological grade, advanced clinical stage and positive regional lymph node metastasis." (PMID 32194777, 2020). "The results indicated that SUSD2 expression was lower in some types of tumors including Lung cancer, colorectal cancer, esophageal cancer, gastric cancer, and sarcoma comparing to their matched normal tissues." (PMID 32194777, 2020). "The four genes with lung cancer-associated alternative splice forms newly identified in this study were: CEACAM1, FHL1, MLPH, and SUSD2." (PMID 20525254, 2010). "In agreement with this postulated role for the protein, we observed reduced expression of SUSD2 in lung cancer tissues." (PMID 20525254, 2010). "The two published work suggested that overexpression of SUSD2 may be an important tumor suppressor in tumorigenesis of lung cancer." (PMID 32194777, 2020). "overexpression of SUSD2 could inhibit the proliferation and clonogenicity of RCC and lung cancer cells, whereas knockdown of SUSD2 could promote lung cancer cell growth." (PMID 32194777, 2020). "Extensive research has indicated that SUSD2 often functions as a tumor suppressor in various types of cancer, including ovarian, colon, endometrial, hepatocellular, retinal (retinoblastoma), and lung cancer, inhibiting cancer cell growth, angiogenesis, and metastasis 13, 14, 18-25." (PMID 39247587, 2024). "Moreover, we used the Kaplan- Meier plotter mRNA lung cancer database to test and verify our results, the consistent results showed that high expression of SUSD2 had a significantly better OS and SUSD2 expression was independent prognostic factors of OS for LUAD patients." (PMID 32194777, 2020). "In particular, SUSD2, CCND2, BCL2A1, and TMEM158 could be potential targets of JFK in human lung cancers." (PMID 27087825, 2016).
serous ovarian cancer (7 papers, 2016 to 2024). "Cancer metastasis can be promoted by SUSD2, which also induces cisplatin resistance in high grade serous ovarian cancer." (PMID 38206646, 2024). "Decreased SUSD2 levels are associated with higher histological grades, clinical stages, and poorer patient survival in HCC and high-grade serous ovarian carcinoma (HGSOC)." (PMID 39791720, 2024). "According to the literature, SUSD2 expression may protect high-grade serous ovarian cancer cells from immune surveillance by inhibiting platelet aggregation and adhesion to cancer cells, which indicates that SUSD2 plays a dual role in various cancer environments." (PMID 39247587, 2024). "Immunohistochemical analysis determined the presence of SUSD2 in several subtypes of EOC, with the strongest staining observed in high-grade serous ovarian carcinomas (HGSOCs)." (PMID 27775699, 2016).
ovarian carcinoma (6 papers, 2016 to 2024). A malignant neoplasm originating from the surface ovarian epithelium. "In the OV_BRCA1 group, we observed overexpression of RCCD1, which was previously identified as a susceptibility locus for ovarian cancer, and of SUSD2, which promotes cancer metastasis and associates with cisplatin resistance." (PMID 33525353, 2021). "Xu Y reported high expression of SUSD2 in ovarian cancer cells contributed to epithelial-mesenchymal transition (EMT) and the metastatic capacity of malignant cells." (PMID 32194777, 2020). "Although the exact mechanism of action remains unknown, results from our animal model suggested that SUSD2 inhibits metastatic spread of ovarian cancer in the abdominal cavity, consistent with findings from our previous study showing that SUSD2 may decrease mesothelial clearance." (PMID 32595828, 2020).
hepatocellular carcinoma (5 papers, 2016 to 2024). A malignant tumor that arises from hepatocytes. "Despite that, the expression status of SUSD2 and its function in hepatocellular carcinoma remain unclear." (PMID 37644393, 2023). "However, the SUSD2 expression status and its functions in hepatocellular carcinoma (HCC) are still unrevealed." (PMID 26933386, 2016).
colon cancer (4 papers, 2016 to 2024). "SUSD2 expression is known to be altered in various types of cancers including colon cancer, non-small cell lung cancer (NSCLC), and gastric cancer." (PMID 39791720, 2024). "In this respect, it is worth noting that GPR15L has been recently reported to interact with SUSD2 to inhibit colon cancer cell growth via G1 arrest, which is induced by down-regulating cyclin D1 and cyclin-dependent kinase 6 (CDK6)." (PMID 38074634, 2023). "SUSD2 is indispensable for the growth inhibitory effect of CSBF/C10orf99 on colon cancer cells and recombinants SUSD2-Fc can block its function." (PMID 26933386, 2016). "However, another study in colon cancer has suggested that overexpression of SUSD2 alone or together with its ligand can inhibit colon cancer colony forming units." (PMID 28841682, 2017).